LOXHD1 (lipoxygenase homology PLAT domains 1)
Description:
Involved in hearing. Required for normal function of hair cells in the inner ear (By similarity).
Synonyms: FLJ32670; LH2D1; DFNB77
Tractability: Antibody: the Human Protein Atlas places it where antibodies can reach. PROTAC: its protein half-life has been measured.
Gene: Protein-coding gene on chromosome 18 (46,476,972 to 46,657,220, reverse strand). Ensembl gene ENSG00000167210.
Subcellular location: Cell projection, stereocilium
Subcellular location (Human Protein Atlas): Plasma membrane
Gene Ontology:
Biological process: sensory perception of sound
Cellular component: stereocilium
Genetic constraint (gnomAD): Loss-of-function variants: 194 observed, 243.95 expected, observed/expected ratio (o/e) 0.8, 90% interval 0.71 to 0.9. The upper end of that interval is the gene's LOEUF score, 0.9, which puts it in group 3 of 6, group 1 being the genes least tolerant of losing a copy. Missense variants: 2,904 observed, 3,035.4 expected, observed/expected ratio (o/e) 0.96, 90% interval 0.93 to 0.99. Synonymous variants: 1,100 observed, 1,192 expected, observed/expected ratio (o/e) 0.92, 90% interval 0.88 to 0.97.
Gene-disease validity (ClinGen):
ClinGen rates the evidence that LOXHD1 causes each of these diseases.
nonsyndromic genetic hearing loss (autosomal recessive): Definitive.
Homologues: Orthologues: chimpanzee LOXHD1 (97% identical), macaque LOXHD1 (96% identical), pig LOXHD1 (95% identical), rat Loxhd1 (94% identical), mouse Loxhd1 (92% identical), guinea pig LOXHD1 (85% identical), tropical clawed frog loxhd1 (59% identical), zebrafish loxhd1b (56% identical), zebrafish loxhd1a (53% identical), dog LOXHD1 (46% identical). Paralogues in human: PKD1 (12% identical), PKDREJ (10% identical), PKD1L2 (9% identical), PKD1L1 (9% identical), PKD1L3 (7% identical), DENND5B (7% identical), DENND5A (6% identical), PKD2 (6% identical), PKD2L1 (5% identical), PKD2L2 (4% identical).
Diseases named in the same sentence as LOXHD1 in open-access papers:
LOXHD1 is named in the same sentence as 36 diseases in open-access papers, as found by Europe PMC text mining. Sharing a sentence is not in itself a finding about the gene and the disease. The quoted sentences say what the papers report.
deafness (20 papers, 2012 to 2025). An inherited or acquired condition characterized by the complete loss of the ability to hear from one or both ears. "Studies suggest that LOXHD1 gene mutation can cause DFNB77-type deafness, which is characterized as a congenital or delayed hearing loss in an autosomal recessive inheritance pattern." (PMID 32149082, 2020). "Loxhd1a and loxhd1b are both homologs of the human deafness gene LOXHD1, the causative gene of DFNB77." (PMID 29765956, 2018). "It is possible that single-cell transcriptome analysis of human utricle cells could also detect the expression of the LOXHD1 gene in striolar cells and, thus, support the association of mutations in this gene with deafness." (PMID 40244234, 2025). "Indeed, many DFNB77 (deafness, autosomal recessive 77) families with complete segregation of LOXHD1 variants have been reported." (PMID 40244234, 2025). "LOXHD1 was the causal gene of autosomal recessive deafness (type 77)." (PMID 32682410, 2020). "Although the LOXHD1 gene (OMIM: #613072) is associated with autosomal recessive deafness, there is a clear association of this gene with corneal dystrophies such as FECD with autosomal dominant inheritance, which may be relevant in the genetic background of keratoconus." (PMID 37895187, 2023). "Mutations in LOXHD1, OTOF, PCDH15, TBL1X, and TMC2 have been associated with hereditary disorders of balance, deafness or hearing loss in humans (NCBI gene db and GeneCards)." (PMID 32770228, 2020). "In this study, we used NGS technology, which led to the identification of novel alleles in SLC26A4, MYO15A, OTOG, LOXHD1, and TBC1D24 that are associated with deafness." (PMID 30139988, 2018). "The analysis of NGS data led to the identification of five novel variants in the known deafness genes MYO15A, LOXHD1, TBC1D24, and OTOG, all of which were associated with pathogenicity, and categorized according to the ACMG guidelines." (PMID 30139988, 2018). "In the Western Romanian population studied, the risk of deafness is given by pathogenic variants in 7 genes included in the panel: GJB2, USH2A, LOXHD1, SLC26A4, USH1C, COL4A4, COL4A3, present in almost 10% of the cohort, therefore representing a significant risk." (PMID 41303398, 2025). "With regard to the responsible gene, the most frequent causative gene was GJB2 (29%), followed by SLC26A4 (9%), CDH23 (7%), MYO7A (4%), OTOF (5%), MYO15A (3%), and LOXHD1 (2%), indicating that these deafness genes are typical deafness genes found in the prelingual CI/EAS patients." (PMID 32027099, 2020). "Twelve homozygous mutations in known deafness genes, of which eight are novel, were identified in 12 families: MYO15A-p.Q1425X, -p.S1481P, -p.A1551D; LOXHD1-p.R1494X, -p.E955X; GIPC3-p.H170N; ILDR1-p.Q274X; MYO7A-p.G2163S; TECTA-p.Y1737C; TMC1-p.S530X; TMPRSS3-p.F13Lfs*10; TRIOBP-p.R785Sfs*50." (PMID 23226338, 2012). "Those in TMC1, CDH23, LOXHD1 and USH2A were each detected in two probands, and those in 10 other deafness genes were each detected in one proband." (PMID 35062939, 2022).
hearing loss (19 papers, 2017 to 2025). "Normothermia TTM upregulated 13 genes associated with hearing loss, including Loxhd1, Tecta, Zmiz1, Espn, Gjb2, Sesn3, Bdp1, Hg, Pax3, Rnls, Syne4, P2rx2, and Pou3f4." (PMID 38298897, 2023). "In our study, patients with sensorineural hearing loss, seizures, epileptic encephalopathy and cardiomyopathy showed mutations in LOXHD1, KCNQ1, KCNQ2 and MYH7 genes." (PMID 33484326, 2021). "As we have described, the severity of the hearing impairment for carriers of the highly penetrant variants in LOXHD1 and FBF1 varies from mild to profound." (PMID 34108613, 2021). "Here, we identified the hearing loss-associated Loxhd1/DFNB77 gene as being required for the mechanotransduction process." (PMID 33707295, 2021). "In conclusion, we describe a rare novel missense variant in LOXHD1 associated with canine autosomal recessive nonsyndromic hearing loss, providing a new animal model for human hearing disorders." (PMID 33983508, 2021). "To summarize, our study describes the first genetic variant for canine nonsyndromic hearing loss, which is clinically and genetically similar to human LOXHD1-related hearing disorder, and therefore, provides a new large animal model for hearing loss." (PMID 33983508, 2021). "We identified a fully segregating missense variant in LOXHD1, a gene that is known to be essential for cochlear hair cell function and associated with nonsyndromic hearing loss in humans and mice." (PMID 33983508, 2021). "By examining a large cohort of hearing loss patients (n = 8,074), we have recently reported 28 patients with LOXHD1 mutations and clarified the clinical features." (PMID 32027099, 2020). "A series of studies have shown that patients with LOXHD1 mutations show progressive hearing loss, leading to profound‐to‐severe non‐syndromic hearing loss." (PMID 32027099, 2020). "Nowadays there have been 47 variants within LOXHD1 associated with hearing impairment according to HGMD database, but c.5948C > T (p.S1983F) was not reported previously." (PMID 30760222, 2019). "Few studies have reported the clinical features of LOXHD1-gene associated hearing loss, and this study is by far the largest study focused on the evaluation of this gene." (PMID 31547530, 2019). "In this study, genetic screening was conducted on 8074 Japanese hearing loss patients utilizing massively parallel DNA sequencing to identify individuals with LOXHD1 variants and to assess their phenotypes." (PMID 31547530, 2019). "Compound heterozygous mutation in LOXHD1 c.4690C > T (p.Leu1564Phe) c.2054G > A (p.Arg685His) and c.5813G > A (p.Arg1938His), c.1191G > T (p.Trp397Cys) was observed in two patients (P2, P4) with hearing impairment." (PMID 33484326, 2021). "LOXHD1 mutation has been previously reported in patients with non-syndromic hearing loss (NSHL)." (PMID 33484326, 2021). "Studies on the association between LOXHD1 mutations and hereditary hearing loss are limited." (PMID 32149082, 2020). "However, previous studies have shown that the onset age of LOXHD1-related hearing loss had a large span, ranging from newborn, prelingual, childhood to even adulthood." (PMID 32149082, 2020). "In particular, the largest study of Italian HHL patients so far carried out, demonstrates the importance of SNP arrays analysis in detecting the first case of UPD in LOXHD1 gene and confirming the importance of genomic rearrangements in the etiopathogenesis of hearing loss." (PMID 30622556, 2018). "This is the first reported LOXHD1 mutation causing hearing loss in China." (PMID 30123251, 2018). "In addition to nonsyndromic hearing loss, an enrichment of LOXHD1 variants in patients affected by Fuchs endothelial corneal dystrophy (FECD) has been observed in one study, suggesting that LOXHD1 could be relevant to the FECD pathogenesis." (PMID 33983508, 2021). "The LOXHD1 gene (DFNB77), encoding lipoxygenase homology domain 1, is a rare hearing loss gene found in several populations." (PMID 35711932, 2022).
hearing loss (continued). "The hearing loss in four other patients was caused by pathogenic biallelic variants in the well-known hearing loss-causing genes: STRC (OMIM 606440); MYO15A (OMIM 602666); SLC26A4 (OMIM 605646); and LOXHD1 (OMIM 613072)." (PMID 34062854, 2021). "Mutations in LOXHD1 cause DFNB77, a human nonsyndromic recessive form of hearing loss that can manifest at birth or later in life and shows various degrees of progression, preferentially affecting the high and middle hearing frequencies." (PMID 33707295, 2021). "First, a G>C missense variant at chr7:44,806,821 in lipoxygenase homology domains 1 (LOXHD1), a gene that is known to cause hearing loss in humans and mice, was predicted to result in a glycine-to-alanine substitution." (PMID 33983508, 2021). "Although the relationship of LOXHD1-related hearing loss and FCD is still unclear, we suggest that ophthalmologic examinations should be performed in patients with ARNSHL when LOXHD1 is suspected to be the pathogenic gene." (PMID 32149082, 2020). "Deafness, autosomal recessive 77 (DFNB77) is a rare non-syndromic hearing loss (NSHL) worldwide, which is caused by deleterious variants within lipoxygenase homology domains 1 (LOXHD1)." (PMID 30760222, 2019). "GS of the remaining 15 cases yielded diagnoses in three individuals, including the identification of deletions in LOXHD1 and STRC, and a recently characterized 125 kb deletion overlapping CRYL1, which refines a critical upstream regulatory region associated with GJB2-related hearing loss." (PMID 41367487, 2025).
Fuchs endothelial corneal dystrophy (3 papers, 2019 to 2023). Fuchs endothelial corneal dystrophy (FECD) is the most frequent form of posterior corneal dystrophy (see this term) and is characterized by excrescences on a thickened Descemet membrane (corneal guttae), generalized corneal edema, with gradually decreased visual acuity. "Similarly, variants in ZEB1, COL8A2, TCF4, FEN1, AGBL1, and LOXHD1 all cause Fuchs endothelial corneal dystrophy (FECD), while the age of onset may vary." (PMID 31555324, 2019).
corneal dystrophies (2 papers, 2021 to 2023). "We did not observe signs of corneal dystrophy in any of the eye examined dogs either homozygous or heterozygous for the LOXHD1 variant." (PMID 33983508, 2021).
Fuchs' endothelial dystrophy (1 paper, 2018). Fuchs endothelial corneal dystrophy (FECD) is the most frequent form of posterior corneal dystrophy and is characterized by excrescences on a thickened Descemet membrane (corneal guttae), generalized corneal edema, with gradually decreased visual acuity. "Multiple genetic loci have been linked to Fuchs' endothelial dystrophy, including but not limited to TCF4, COL8A2, SLC4A11, ZEB1 and LOXHD1." (PMID 29685994, 2018).
hearing (1 paper, 2019). "Patients with LOXHD1 variations mostly showed early onset hearing loss and presented different progression rates." (PMID 31547530, 2019).
hearing disorder (1 paper, 2021). A disorder characterized by the partial or complete loss of the ability to detect sounds due to damage to the ear structures or inability of the brain to properly interpret or process the auditory signals it receives from the anatomic structures of the ear. "Equally important, the affected breed will benefit from a genetic test to eradicate this LOXHD1-related hearing disorder from the population." (PMID 33983508, 2021).
invasive breast carcinoma (1 paper, 2017). A carcinoma that infiltrates the breast parenchyma. "Same like, the detected LOXHD1 missense mutation in Jed81_MT has been previously detected in an invasive breast carcinoma (COSM1480342)." (PMID 29287594, 2017).
prostate carcinoma (1 paper, 2022). A carcinoma that arises from epithelial cells of the prostate gland. "In SK-N-MC and RD-ES cells, LOXHD1 staining was observed on both the plasma membrane/cytoplasm and in the nucleus, whereas prostate cancer cell line LNCaP used as a negative control displayed no specific staining." (PMID 35705030, 2022).
sarcoma (1 paper, 2022). A usually aggressive malignant neoplasm of the soft tissue or bone. "Remarkably, the invasive potential of LOXHD1-proficient EwS cells was amplified under hypoxic conditions confirming earlier reports that hypoxia promotes sarcoma invasion and metastasis." (PMID 35705030, 2022).
cancer (3 papers, 2017 to 2023). A tumor composed of atypical neoplastic, often pleomorphic cells that invade other tissues. "Very little is known about the role of LOXHD1 in normal cell physiology or in cancer, due to its undetectable expression in a large majority of normal or cancer cells." (PMID 35705030, 2022). "Except for a study showing that a missense mutation in mouse LOXHD1 affects the function of the sensory cells involved in hearing, not much is known about its role in normal or cancer cell physiology." (PMID 35705030, 2022). "In summary, our findings identify LOXHD1, which is transcriptionally silent in the vast majority of normal and cancer cells, as a direct EWSR1::FLI1 target gene that plays an important role in cytoskeletal homeostasis, hypoxic adaptation, and oncogenic transcription in EwS." (PMID 35705030, 2022). "However, little is known about LOXHD1 expression and function in normal physiology and cancer." (PMID 35705030, 2022).
genetic disorder (1 paper, 2025). "A GJB2 gene mutation was found in 4.3% (4/92) of patients with simultaneous CI, whereas 15% (6/40) of patients with sequential CI had a genetic disorder such as mutations in GJB2 gene, DFNBA1 gene and LOXHD1 gene." (PMID 41142164, 2025).
infection (1 paper, 2022). The state of being infected such as from the introduction of a foreign agent such as serum, vaccine, antigenic substance or organism. "Infection with single guide RNA (sgRNA) Cas9 lentivirus targeting regions on either side of the GGAA repeat led to the deletion of approximately 172 bp DNA and a concomitant decrease in the transcription of LOXHD1 in a pool population of SK-N-MC and RD-ES cells." (PMID 35705030, 2022).
tumor (1 paper, 2022). "LOXHD1 meets the criteria for a potential oncogene, a diagnostic marker and exquisitely specific tumor antigen for potential adoptive cell-based therapy." (PMID 35705030, 2022). "Second, the rarity of fresh tumor specimens also hindered us from testing the role of LOXHD1 in patient-derived tumor models." (PMID 35705030, 2022). "Together, these in vivo data clearly establish the role of LOXHD1 in regulating EwS tumor formation and metastasis." (PMID 35705030, 2022). "Here, we use an integrative RNA-sequencing (RNA-seq)-based approach, coupled with chromatin immunoprecipitation sequencing (ChIP-seq) and tumor cell functional studies, to identify stereociliary protein LOXHD1 as a gene product specifically expressed in EwS." (PMID 35705030, 2022). "Compared with parental control, the LOXHD1-silenced SK-N-MC xenograft demonstrated a significantly reduced tumor growth, which was accompanied by increased necrotic margins and lower mitotic foci." (PMID 35705030, 2022). "Finally, to examine the role of LOXHD1 in EwS tumor growth and metastasis in vivo, we used three different metazoan models, namely the chicken chorioallantoic membrane (CAM) model, zebrafish model, and mouse xenograft model." (PMID 35705030, 2022).
LOXHD1 also shares sentences with these, for which no sentence is quoted: autosomal recessive deafness (2 papers); Hearing impairment (2); asthma (1); cardiomyopathy (1); diabetes (1); Endothelial dystrophies (1); epilepsy (1); Epileptic encephalopathy (1); Ewing sarcoma (1); hippocampal atrophy (1); interstitial lung disease (1); keratoconus (1); maturity-onset diabetes (1); MELAS (1); mitochondrial disease (1); Mitochondrial encephalopathy (1); osteosarcoma (1); sensorineural hearing loss (1); syndromic (1); systemic sclerosis (1); Vertigo (1); Visual impairment (1).